IL6 (interleukin 6)
Diseases named in the same sentence as IL6 in open-access papers (continued):
Sharing a sentence is not in itself a finding about the gene and the disease.
infection (continued). "Proinflammatory cytokines, such as IL-6, IL-1β, and TNF-α, play an essential role in infection-induced inflammatory responses." (PMID 34829902, 2021). "Among the different cytokines and chemokines produced at the initial phase of the inflammatory process, IL-8, and particularly IL-6 and TNF-α have been extensively studied in inflammatory diseases and infections." (PMID 33708198, 2021). "Notably, STING-KO-infected mice had significantly lower IFN-β and IL-6 gene expression in the spleen at day 4 after infection when compared with C57BL6-infected mice, indicating that STING-dependent signaling may play a role in early induction of key cytokines against T. cruzi." (PMID 35095849, 2021). "Previous work showed that infection with HP influenza viruses such as H5N1 and H5N6 is characterized by the elevation of IL-6 and IL-8, along with the interferons as contributing factors to apoptosis." (PMID 33808583, 2021). "The lung and trachea homogenates from all animals had detectable cytokines (IL-6, IL-1α, IL-1β, TNFα and TGFβ) and chemokine (MCP-1) at Day 7 post-infection." (PMID 34452519, 2021). "The classically activated M1 macrophages secrete proinflammatory cytokines, such as IL-1β, IL-6, IL-12, IL-23, and TNF-α, in response to stress and infection." (PMID 34360840, 2021). "S.pn infection led to significantly increased inflammatory cytokine levels of TNF-α, IL-1β, and IL-6 in BALF (p < 0.01), while QFY treatment of infected mice led to significantly decreased BALF levels of these cytokines." (PMID 34950611, 2021). "S.pn infection led to significantly increased inflammatory cytokine levels of TNF-α, IL-1β, and IL-6 in BALF (p < 0.01)." (PMID 35111047, 2021). "Total bone marrow and spleen cells from 24 h post-secondary infection were cultured and stimulated with PMA and ionomycin for 6 h to assess cytokine production (TNF-α and IL-6) by LKS+ and LKS– cells by intracellular flow cytometry." (PMID 34975887, 2021). "The expression levels of interleukin (IL)-6 and CXCL1/CXCL2 in MZ B cells increased significantly in mice at 3–4 h after infection with S. aureus, then decreased at 24 h post-infection." (PMID 34040603, 2021). "Expression of CRP is induced by IL-6 and other cytokines (IL-1β, TNF) via NF-κB and other transcription factors as part of the acute-phase response or during inflammatory conditions and infections." (PMID 34925360, 2021). "The manifestation of severe dengue infections occurs during the critical phase of the infection, and levels of pro-inflammatory cytokines, such as TNF-α and IL-6, become elevated, which leads to further disease progression and causes DHF/DSS." (PMID 34912307, 2021). "IL‐1β, IL‐6, and TNF‐α are important for acute phase protein production and fever induction, while IL‐12, IL‐18, and IFN‐γ recruit neutrophils to the site of infection and elicit a T helper type 1 (Th1) adaptive immune response." (PMID 33970545, 2021). "At the moment of infection, the promastigotes encountered an environment of high TGF-β gene expression and intermediary basal TNF, IL-6, and IL-4 gene expressions." (PMID 34276650, 2021). "Multiple factors contribute to neutrophil recruitment from the circulation to the site of infection, including proinflammatory cytokines (such as IL-1α, IL-1β, TNF-α, and IL-6) and Cxcr2 chemokines (such as Cxcl1, Cxcl2, Cxcl5, and Cxcl8)." (PMID 34011393, 2021). "In addition, the highly induced CPs (P < .0001) at 2 h post-infection were Neuroinflammation Signaling, TLRs, PPRs, IL-6, and NF-kB Signaling; while at 24 h, the highly induced CPs (P < .0001) were TLRs, Neuroinflammation Signaling, PPRs, IL6, and TREM1 Signaling." (PMID 33382951, 2021). "Under inflammatory conditions, there was an increased activation of IL-1β, IL-6, IL-8, TNF-α in MDCK cells following infection with C. jejuni RC039, S. enterica and C. perfringens." (PMID 34099034, 2021).
infection (continued). "After MIA induction by infection, IL-6 in maternal serum is elevated, and placental SOCS3 and CRH are upregulated in response to the increased IL-6." (PMID 34350170, 2021). "Interleukin-6 (IL-6)—IL-6, IL-11, LIF, and OSM are several of the members of an important family of mediators involved in acute-phase response to injury and infection but are also critical to hematopoiesis." (PMID 34681039, 2021). "The cytokine levels in natural course of infection have been investigated in a number of studied and IL-6, IL-10, TNF-α and IFN-γ were found to be major cytokines during the natural course of infection." (PMID 34851958, 2021). "In this connection, interleukin-6-mediated induction of Zip14/SLC39A14 is known to mediate the uptake of zinc into the liver during acute inflammation and infection, which is believed to be host defensive." (PMID 35058926, 2021). "These virulence factors are immunomodulatory and, indeed, infection with the dnj1∆ mutant revealed impaired induction of the cytokines IL-6, IL-10, and MCP-1 in the lungs of mice compared to infection with wild type or complemented strains." (PMID 34566931, 2021). "Expression of SOCS-1 during infection correlates with reduced levels of the pro-inflammatory cytokines IL-1β, TNF-α, and IL-6 as well as antimicrobial NO and reactive oxygen species (ROS)." (PMID 33690673, 2021). "For instance, when tested in a human whole blood ex vivo model of infection, a PIA-positive S. epidermidis strain (SE1457) induced lower levels of TNF-α, IL-6, IFN-γ production than its PIA-negative isogenic mutant (M10)." (PMID 34576742, 2021). "But currently, there are no recognized standard biomarkers to assess SCI levels alone, and SCI is typically measured by combining biomarkers of acute inflammation and infection, e.g., CRP, IL-6, and TNFα." (PMID 34925360, 2021). "Consistently, in both high and low dose infections with the H5N1, substantially high levels of IL-6 responses were detected even in immunized mice." (PMID 34684240, 2021). "The results illustrated that infection with the S. choleraesuis significantly upregulated the mRNA levels of TNF-α and IL-6 in the colon." (PMID 35051090, 2021). "(F) RT-PCR analysis of IFNB1, IFIT2, IFIT1, TNF, IL6, and CCL20 mRNA levels in HEK293T cells transfected with HA-Ev or HA-RTN3 followed by infection with VSV-eGFP (MOI = 1) at the indicated timepoints." (PMID 34313226, 2021). "Neutrophil recruitment in the blood and at infection sites is orchestrated by chemotactic cytokines/chemokines, including GM-CSF, CXCL1/2, TNF-α, and IL-6." (PMID 34899755, 2021). "Transcription levels of four major proinflammatory cytokines, IL6, IL8, IL1β and TNFα, were examined at different times post infection." (PMID 33712643, 2021). "Of the seven inflammatory mediators that increased in the late stage of infection in the mice that received vehicle, three—TNF-α, IL-6, and IP-10—were significantly in both the early and late phases." (PMID 34835277, 2021). "The cytokines, such as IL6 and IL8, released by inflammatory cells are essential factors in resisting pathogen infection." (PMID 34407874, 2021). "Moreover, it has been shown that the intraperitoneal administration of proinflammatory cytokines (IL-1, TNF-α, and IL-6), alone or combined, temporally induces anhedonia and that infection with bacteria of the genus Mycobacterium may also produce memory deficits and anhedonia." (PMID 34576830, 2021). "The expression levels of the cytokines IL-6, IL-8 and TNF-α in the infected group were significantly higher than those in the control group at 12 h and 24 h post-infection." (PMID 34674760, 2021). "In this study, the levels of pro-inflammatory cytokines, including IL-1β, IL-6, TNF-α and IFN-γ, were elevated after infection, suggesting the innate immunity was activated by PRV." (PMID 34275451, 2021).
infection (continued). "As evident from in vitro study by one of the authors, induction of inflammatory cytokines/chemokines including IL-6, IL-8, TNF-α, and RANTES was observed within 12 h of infection in genotype 1 HEV infected lung epithelial cells." (PMID 34502167, 2021). "Additionally, IL-6 and TNF-α have been shown to be permeable to the blood-brain barrier, with potential interactions with the hypothalamus to induce subjective feelings of sickness and associated behaviors as a self-defense strategy during fevers in response to an infection." (PMID 33642989, 2021). "On the other hand, MoDCs infection by HSV-2 produced a significant increase in TNF-α and IL-6 expression, with a reduced expression of IFN-β and IL-12p70, and a modest synthesis of IL-10." (PMID 34895058, 2021). "At both post-infection periods, FICZ increased the numbers of CD11c+ cells expressing IL-12, IL-6, TGF-β and IL-10." (PMID 33936043, 2021). "Pan-caspase-inhibition during MVA-infection similarly led to increased TNF and IL-6-secretion, whereas the IFN-I response was induced by additional QVD treatment in Bax/Bak-double-deficient, but not wt cells." (PMID 34711816, 2021). "The serum levels of IL6, IL8, IL12 and Transforming growth factor beta 1 (TGFβ1) showed a more pronounced increase at the early infection stages with the PCV2 virus in the Laiwu pigs compared to YL pigs." (PMID 34407874, 2021). "In particular, S. aureus-induced infection determines a deregulated production of pro-inflammatory cytokines, including tumor necrosis factor alpha (TNF-α) and interleukin-6 (IL-6), as well as of several chemokines." (PMID 33430251, 2021). "We found upregulation in expression of the proinflammatory cytokines IL-1β, IL-6, TNF-α, and IL-12p35 as well as the chemokine CXCLi1 in chMoDCs treated with S. Typhimurium during the early phase of infection (6 h)." (PMID 34446765, 2021). "NF-κB is believed to be a major regulator of inflammation, and IL-1β, IL-6 and TNF-α are rapidly released in response to tissue injury or infection." (PMID 35096806, 2021). "Our results revealed that DATS significantly reduced the expression of IL-6 and TNF-α in H9N2 AIV-infected cells and enhanced the expression of RIG-I and IFN-β in the lungs to defend H9N2 AIV infection in mice." (PMID 34412671, 2021). "In the present study, the mRNA expression of inflammatory cytokines (IL-1β, IL-6, TNF-α) in the trachea and lung of group IV was lower compared with the expression levels of other groups from day 1 to 7 post-infection." (PMID 34988139, 2021). "In the present study, the IL-6, IL-10 and TGF-β productions varied in their levels of increase at different days post-infection, which is similar to the observation made in a study on T. spiralis infection in large white pigs." (PMID 33639942, 2021). "On the other hand, murine intradermal infection with the herpes simplex virus (HSV)-2 induced the synthesis of IL-33 by keratinocytes, that in turn activated the synthesis of TNF-α and IL-6 by MCs, key cytokines in reducing the severity of the infection." (PMID 34211473, 2021). "The percentage of IFN-γ-secreting CD8+ T cells increased significantly after infection (P < 0.05), while it decreased significantly in infected TLR7 KO mice, as well as IL-2 and IL-6 (P7 < 0.05)." (PMID 34692568, 2021). "Therefore, early detection of IL6 may provide an early indication of severe infection." (PMID 34731090, 2021). "Expression of IL-6, IL-18, TNF-α, IFN-γ, and CCL2 increase within 24 h of infection of P815 cells with either a H1N1, H5N1, or H7N2 strain of IAV." (PMID 33680987, 2021). "For instance, serum and plasma from patients with a mild to moderate infection contained significantly greater levels of MCP-3, IL-1α, TNFβ, IL-4, IL-5, IL-6, IL-8, IL-9, and IL-13 compared to serum and plasma from patients that were critically ill." (PMID 34790978, 2021).
infection (continued). "It has been showed that IL-6 promotes B. abortus clearance in macrophages and CD8 + T cell differentiation, priming the Th1 response during infection." (PMID 34078437, 2021). "As observed for infection, STING-KO cells had significantly lower IFN-β, IL-6, and IL-12 gene expression in response to T. cruzi DNA." (PMID 35095849, 2021). "During infection, PR signals to APC are responsible for inducing their ability to make high levels of IL-6 during subsequent cognate interaction, so this suggests higher levels of PR signals are needed in the aged." (PMID 35382063, 2021). "The IL-6 levels of patients with negative nucleic acid results were slightly increased when the days post onset (dpo) were longer than 75 days, and this might be caused due to a long term infection and several methods of medical treatment." (PMID 33746945, 2021). "LF pre-infection treatment (unwashed) also significantly decreased the expression of IL1B and IL6 mRNA, whereas pre-infection treatment (washed) left it unchanged." (PMID 33498631, 2021). "Infection of chicken dendritic derived cell with virulent NDV elicited MD5, TLR3, TLR7, interferons, IL1β, IL-6, IL-18, 1L-10, and IL-12 production and the relative levels of expressions depend on the strain pathogenicity." (PMID 33406695, 2021). "The virus-induced infection elicits inflammatory manifestations (absolute lymphocyte count and levels of LDG, CRP, ferritin, D-dimer, and IL-6) that correlate with a CS scenario (lymphocytopenia, hypercytokinemia, hyperinflammation)." (PMID 34858403, 2021). "Surprisingly, infection with the Δrgg3 mutant led to approximately 4-fold decreased NF-κB reporter activity and 20-fold decreased TNF-α and 25-fold decreased IL-6 production compared to infection with WT or Δrgg2 strain." (PMID 33947757, 2021). "Infections with Rift Valley Fever virus (RVFV) clone 13 (for IFN-α) or stimulation with LPS/IFN-γ (for TNF-α and IL-6) were performed as positive controls." (PMID 34122407, 2021). "We performed an infection with Gram‐positive bacteria L. monocytogenes at a multiplicity of infection of 10 in macrophages and found that the silencing of RNF10 showed a higher production of IL‐6 and TNF‐α after infection for 6 h." (PMID 33249776, 2021). "Biological pathway analysis showed that HSPCs are producing proinflammatory cytokines, such as TNF-α and IL-6, in response to the PCA2 infection and especially after the ATCC 26555 secondary infection." (PMID 34975887, 2021). "Downregulation of multiple pro-inflammatory genes (CCL5, IL6, IL1B) was accompanied by upregulation of anti-inflammatory TNFAIP3 at 48 h post-infection." (PMID 34759825, 2021). "TNF-α, IL-Iβ, IL-6 and IFN-γ, belonging to the pro-inflammatory cytokines, are involved in promoting acute inflammation to defense against infection." (PMID 34275451, 2021). "Whereas AM mainly produce (TNF)-α after 6h of infection with conidia, murine AEC mainly produce (IL)-6 after 10h." (PMID 34898608, 2021). "They both regulated the intensity of immune responses to XPa in mice, and no severe inflammatory responses were observed in immunized mice (the levels of the inflammatory factors IL-6, TNF-α and IL-8 were lower than those of Infection group mice)." (PMID 34593766, 2021). "RAW264.7 cells and BMDMs infected with rMS::pMV261-Rv0927c induced a decrease in IL-6, TNF-α, and IL-1β expression, compared with those infected with rMS::pMV261 at 6, 24, and 48 h post-infection." (PMID 34531869, 2021). "Previous studies have shown the importance of macrophage TLR2 activation for the secretion of IL-1β, IL-6, TNF-α, IFN-β during the infection with L.m." (PMID 34194428, 2021). "T-helper cell (Th1)-type cytokines, such as TNF-α, IL-6 and IL-1β, and Th2-type cytokines, such as IL-10 and IL-4, were differentially expressed in M. fortis and BALB/c mice in the early stage of infection." (PMID 34689797, 2021).
infection (continued). "At early time points of C. albicans infection, Trim31−/− mice showed significantly reduced secretion of IL-6, TNF-α, IL-12, CXCL1, and CXCL2 in their serum at 24 h post-infection as compared with Trim31+/+ mice." (PMID 34362877, 2021). "Numerous studies have shown that monocytes stimulated with sCD100 produce the pro‐inflammatory cytokines IL‐6, IL‐8 and TNF‐α51 and that sCD100 also augments infection and phagocytosis." (PMID 34414666, 2021). "The BCG-CWS-adjuvanted (S+BCG-CWS) vaccination effectively attenuated the production of inflammatory cytokines including IL-6, TNF-α, and IFN-γ, in the lungs from all aged mouse groups (6 D, 2 W, 6 W, and 20 M) after lethal infection." (PMID 34063125, 2021). "CD8+ T cells (T) are subsequently recruited to the infection site following a delay to account for antigen presentation, with expansion modulated by type I IFN and IL-6 concentrations." (PMID 34260666, 2021). "Burned mice infected with P. aeruginosa M2 showed increased circulating proinflammatory cytokines (IL-6, IL-1β, TNF-α, and IFN-γ) and a rise in anti-inflammatory IL-10 late during infection once clinical symptoms were observed." (PMID 34152806, 2021). "As expected, MVA-infection strongly induced secretion of type 1 interferons (IFN-I) and the IFN-stimulated gene products CXCL10 and CCL5 in macrophages, as well as IL-6, TNF, and GM-CSF." (PMID 34711816, 2021). "Another study in adult hematology patients with probable/possible IA reported higher levels of cytokine IL-6 and chemokine IL-8 in serum and significant elevations in bronchoalveolar lavage (BAL) fluid levels of IL-8, compared to those with other infections." (PMID 34575791, 2021). "The infection and fatal groups showed considerable increases in several inflammatory factors (gamma interferon [IFN-γ], interleukin 6 [IL-6], IL-8, SIRT2, CCL3, and CXCL10) compared to the control group." (PMID 33593977, 2021). "The expression of IL-1β, IL-6, IL-8, IL-18, TNF-α, MMP-9, RANKL, TLR-2, TLR-4, TLR-6, thymic stromal lymphopoietin (TSLP), and ICAM-1 was evaluated by qPCR at 2 and 24 h after infection." (PMID 33802988, 2021). "Transcripts for MDA5 and retinoic acid-inducible gene-1 were found up-regulated after the infection of MCs with DENV and with VSV, leading to the synthesis of IL-6, IFN-β and IFN-α during VSV infection." (PMID 34211473, 2021). "The levels of cytokines (IL-6, TNF-α, IL-1β) and chemokine (CCL2) were upregulated in response to the B.1.1.7 and B.1.351 infection in the lungs." (PMID 35062231, 2021). "ELISA and qRT-PCR assays indicated that Tat mutant infection significantly induced proinflammatory cytokine (TNF-α and IL-6) and nitric oxide (NO) production." (PMID 34195100, 2021). "During infection inflammatory cytokines such as tumor necrosis factor α (TNF-α), interleukin-1 (IL-1) and/or interleukin-6 (IL-6) are enhanced." (PMID 32854285, 2020). "The frequency of BMMCs producing IL-6 and TNF-α decreased between 16 and 20 h post-infection in IFNAR-intact cells from 16.05% ± 2.51% and 15% ± 1.21% to 5.87% ± 0.64% and 7.92% ± 0.88%, respectively." (PMID 33261178, 2020). "The levels of IL-1β, IL-6, and TNF-α in serum and lung samples were compared between innate immune effector depleted mice and control mice 24 h after infection." (PMID 33163539, 2020). "Mtb-infected IL-6−/− mice, as the present study demonstrates, exhibit a reduced polyclonal TH17 immune response over the entire course of infection." (PMID 33375150, 2020). "The elevated levels of the IL-6 and TNF-α induced by infection were significantly decreased by more than 70% after the treatment with EH." (PMID 32528422, 2020). "Infection triggers heavy cellular immune reactions in fish, with elevated level of TNF-alpha, IL-1beta, IL-6, and IgM." (PMID 33003479, 2020). "Although TNF-α, IL-6, and IFN-γ were reduced by 5 weeks post-infection, they were still significantly elevated relative to uninfected controls (white background)." (PMID 32973293, 2020).